CNDP2 (carnosine dipeptidase 2)
Diseases named in the same sentence as CNDP2 in open-access papers (continued):
Sharing a sentence is not in itself a finding about the gene and the disease.
tumor (21 papers, 2014 to 2025). "CNDP2 is frequently overexpressed in various cancers and has been implicated in tumor cell proliferation and progression." (PMID 41302428, 2025). "Concordant with this tumor-suppressive effect, the expression level of CNDP2 is inversely correlated with progression risk." (PMID 41134301, 2025). "In contrast to loss of the tumor-suppressive functions of CNDP2, we note that Glucose-6-phosphate isomerase (GPI) expression is associated with increased risk of progression." (PMID 41134301, 2025). "Functional studies have indicated that CNDP2 knockdown inhibits tumor growth; however, the exact mechanisms underlying its oncogenic roles remain unclear." (PMID 41302428, 2025). "Besides maintaining redox balance, recent studies have implicated CNDP2 in tumor biology." (PMID 41302428, 2025). "Recent studies have revealed that CNDP2 facilitates tumor cell fitness through a cooperative nutrient scavenging mechanism, particularly under conditions of glutamine deprivation." (PMID 41302428, 2025). "For example, in ovarian cancer, CNDP2 promotes tumor growth and metastasis by activating the PI3K/AKT signaling pathway." (PMID 41302428, 2025). "Genetic ablation or pharmacological inhibition of CNDP2 suppresses peptide-dependent growth in vitro and reduces tumor burden in vivo, whereas glutamine supplementation restores these phenotypes." (PMID 41302428, 2025). "Remarkably, long-term coculture competition and in vivo experiments revealed that non-cooperative (CNDP2 mutant) cells which only consume nutrients did not survive better but rather were driven to extinction by cooperative (CNDP2 wildtype) tumor cells." (PMID 40350469, 2025). "The study by Guzelsoy has contributed to a better understanding of intratumoral cooperation and has identified CNDP2 as a target structure with great therapeutic potential for tumor extinction." (PMID 40350469, 2025). "CNDP2 is upregulated in several tumors and appears to act as a tumor suppressor in hepatocellular carcinomas and in gastric cancer, which appears to be achieved by stimulating MAPK, notably p38 and JNK, thereby inducing apoptosis." (PMID 37175751, 2023). "Adding to this heterogeneity, it has to be determined whether the CNDP2-dependent nutrient scavenging operates likewise in all tumors, tumor sites and tumor patients, respectively." (PMID 40350469, 2025). "Using different elegant experimental and analytical approaches in human and murine model systems, the authors identified a cooperative mechanism that relies on distinct tumor cells secreting the aminopeptidase CNDP2 which then hydrolyses extracellular oligopeptides." (PMID 40350469, 2025). "CNDP2 acts as a tumor suppressor, the upregulation of which leads to an activation of the p38 and JNK/MAPK pathways (thereby leading to cell apoptosis), while its downregulated expression results in an activated ERK/MAPK pathway that can promote cell proliferation." (PMID 36038612, 2022). "Therefore, inhibiting CNDP2 may disrupt the redox balance and sensitize tumor cells to oxidative stress, which is a rational strategy for cancer therapy; however, the established inhibitor BES is limited by poor selectivity and suboptimal drug-like properties." (PMID 41302428, 2025). "Furthermore, the therapeutic efficiency of CNDP2 targeting might be enhanced by combination with other strategies interfering with the immunosuppressive tumor ecosystem, e.g., immune checkpoint inhibitors." (PMID 40350469, 2025). "The discrepant expression of CNDP2 in different tumours may due to its tissue specificity." (PMID 24587265, 2014). "Finally, down-regulation of CNDP2 inhibited tumor formation in nude mice." (PMID 24885395, 2014). "When tumor cells gain the ability to overexpress CNDP2, the elevation in GSH content would render tumor cells resistant against anticancer agents." (PMID 37175751, 2023).
tumor (continued). "Downregulation of proteins involved in the mitochondrial respiratory chain like NFU1, ACO2, PDHA1, and proteins like DECR1, CNDP2, and SPINT1, which have a tumor suppressive role in different cancers were noted." (PMID 34885041, 2021). "Carnosine dipeptidase 2 (CNDP2) represents an attractive therapeutic target because of its roles in maintaining intracellular cysteine availability for glutathione synthesis and supporting tumor cell proliferation through nutrient recycling." (PMID 41302428, 2025). "However, not all tumours express a low CNDP2 level, and the molecular function of CNDP2 is largely unknown." (PMID 24587265, 2014).
cancer (12 papers, 2011 to 2025). A tumor composed of atypical neoplastic, often pleomorphic cells that invade other tissues. "CNDP2 expression is increased in various cancers and is frequently associated with malignancy." (PMID 41302428, 2025). "Taken together, these findings establish KKL-35 as a validated CNDP2 inhibitor and a promising lead compound for the development of more selective therapeutics targeting CNDP2-mediated cancer cell metabolism." (PMID 41302428, 2025). "In cancer, CNDP2 has been observed to activate the PI3K/AKT and MAPK signalling pathways, upregulate key cell cycle proteins (e.g. cyclin E, cyclin B1) and interact with pepsinogen C." (PMID 39349903, 2025). "In this study, we combined virtual screening with a molecular dynamics simulation pipeline to identify novel CNDP2 inhibitors with improved specificity and therapeutic potential for cancer treatment." (PMID 41302428, 2025). "Expression of the CNDP2 gene is frequently up- or down-regulated in different types of human cancers." (PMID 30885138, 2019). "We speculate that lactate can deplete amino acids in CNDP2+ ccRCC cells, thereby inhibiting the mTORC1 signaling pathway and exerting an anti-cancer effect." (PMID 40739140, 2025). "CNDP2 was also found to be involved in the regulation of the cell cycle in human cancer cell lines." (PMID 30885138, 2019). "Many studies reported that the CNDP2 gene is misexpressed in different types of human cancers." (PMID 30885138, 2019). "Our work demonstrated that CNDP2 promoted the growth of cancer cells." (PMID 24885395, 2014). "As protein degradation is a central feature of cancer cachexia, we next compared the mRNA levels of CARNS, TauT, PHT1, and CNDP2 between the three groups." (PMID 37199284, 2023). "In most cases, PFN1, NCL and CNDP2 exerted an increased mRNA expression, while OGN displayed a decreased level in the carcinoma tissues compared with the adjacent normal tissue." (PMID 24587265, 2014).
nephropathy (2 papers, 2013 to 2025). A nonspecific term referring to disease or damage of the kidneys. "The association between CNDP2 and cardiometabolic and renal diseases is also explored, and knowledge gaps are highlighted." (PMID 39349903, 2025). "Although the physiological role of CNDP2 in humans is incompletely understood it may play a role in the development of cardiometabolic and renal diseases." (PMID 39349903, 2025).
CNDP2 also shares sentences with these, for which no sentence is quoted: Lymph node metastasis (4 papers); diabetes (3); infection (3); renal cell carcinoma (2); autism (1); breast carcinoma in situ (1); Cardiovascular Diseases (1); colon disease (1); end-stage renal disease (1); gastric adenocarcinoma (1); Hypertension (1); inflammation (1); liver cancer (1); lung adenocarcinoma (1); male infertility (1); melanoma (1); myocardial infarction (1); neuroblastoma (1); periodontal disease (1); rectal cancer (1); signet ring cell adenocarcinoma (1); Stroke (1); substance abuse (1); triple-negative breast carcinoma (1); tuberculosis (1); type 2 diabetes (1).